BRCA1 (BRCA1 DNA repair associated)
Diseases named in the same sentence as BRCA1 in open-access papers (continued):
Sharing a sentence is not in itself a finding about the gene and the disease.
breast tumors (continued). "Here, we explore the role of the α6-integrin in mammary tumorigenesis, using an established mouse model of basal-like cancer, the Blg-Cre;Brca1F/F;Trp53F/F mice, that develop invasive tumors phenocopying BRCA1-deficient human breast tumors at the molecular and morphological level." (PMID 38835038, 2024). "Additionally, Ki67 ≥ 15% was one of the independent predictors for a BRCA1/2 mutation, as most BRCA1/2 mutation carriers have breast tumors with vigorous mitosis." (PMID 38167124, 2024). "Notably, deregulation of luminal ER/PR- progenitors is believed to be at the origin of basal-like breast tumors, particularly those associated with Brca1 mutations." (PMID 38835038, 2024). "In contrast to the well-established PARPi-resistance mechanisms based on restoration of BRCA1/2 pathway functions, we identify an adaptive mechanism driven by PGF-FLT1-AKT signaling that protects Brca1- and Bard1-deficient breast tumor cells from PARPi-induced cell death in-vivo." (PMID 38956205, 2024). "BRCA1 mutation may lead to a disruption of the BRCA1-ACCα complex, which, in turn, increases ACCα release and lipogenesis in breast tumor cells, indicating that the ACCα activity could be essential for BC cells survival." (PMID 37370164, 2023). "In addition, these BRCA1-associated breast tumors are usually triple-negative for estrogen receptor α (ER-), progesterone receptor (PR-) and HER2 (HER2-), which makes the development of targeted therapies difficult." (PMID 37108398, 2023). "However, in all nine BRCA1/2 mutated ovarian and breast tumors, a high LOH value was detected, indicating a stronger association between both genes and LOH positivity in these tumor types." (PMID 37761329, 2023). "Such a scenario could allow for breast tumor cells with BRCA1 mutations to evade the immune system, elevating the BC risk in women with BRCA1 mutations." (PMID 38275383, 2023). "The repair deficiency may partly relate to a diabetes-associated downregulation of BRCA1/2 function in breast tumors, as our data suggest, and to metabolic alterations that increase oxidative stress and reduce the availability of α-ketoglutarate." (PMID 37906280, 2023). "BRCA1-associated breast tumors show less DNA methylation compared to sporadic breast tumors." (PMID 37108398, 2023). "However, several reports have shown that BRCA1 expression loss in Her2-positive sporadic breast tumors is associated with worse prognostic features (e.g., higher histological grade, increased proliferation), early progression, and a poor survival rate." (PMID 37627161, 2023). "Moreover, the TNBC subtype is frequently seen in breast tumors arising in the BRCA1 mutation carriers (70%) and BRCA2 carriers (16–23%)." (PMID 35566456, 2022). "Mechanistically, BRCA1-deficient breast tumor cells induce pro-tumor polarization of TAMs, which in turn suppress PARPi-elicited DNA damage in tumor cells, leading to reduced production of dsDNA fragments and synthetic lethality, hence impairing STING-dependent anti-tumor immunity." (PMID 35641483, 2022). "Since BRCA1-deficient breast tumor cells have reduced production of dsDNA fragments upon PARPi in the presence of TEMs/TAMs, we wondered whether an exogenous STING agonist could alter macrophage state and tumor cell response to PARPi." (PMID 35641483, 2022). "The XIST RNA domain number in BRCA1 breast tumor was associated with chromosomal genetic abnormalities, and XIST might become a predictive biomarker for prognosis of patients with BRCA1 breast tumor." (PMID 36212008, 2022). "Homologous recombination (HR) deficiency confers exquisite sensitivity to poly (ADP-ribose) polymerase (PARP) inhibitors (PARPi), which have been therapeutically exploited in both ovarian and breast tumors carrying loss-of-function mutations in HR pathway genes, most commonly BRCA1 and BRCA21." (PMID 35641483, 2022).
breast tumors (continued). "Our group previously showed that EZH2 is functionally relevant in BRCA1-deficient breast tumors and blocking EZH2 enzymatic activity could be a potent treatment strategy." (PMID 35715861, 2022). "Meanwhile, PR expression in BRCA1-associated tumors is lower than that in sporadic tumors, thus making breast tumors in patients with BRCA1 mutations more likely to be classified as triple-negative breast cancer, characterized by the loss of ER and PR expression and HER2 overexpression." (PMID 35402620, 2022). "Similarly, breast tumors adopt AS events to remove deleterious germline BRCA1 mutations by removing exon 11 to contribute to retaining activity and drug resistance." (PMID 36466711, 2022). "Additionally, 36 of the 40 BRCA1-associated DV genes were also DV between BRCA1-associated and sporadic breast tumours." (PMID 34287743, 2021). "BRCA1-deficient and BRCA2-deficient tumors have distinct T cell and myeloid populations that impact response to immunotherapy, and low expression of BRCA1 protein in breast tumors is associated with increased CD8+ T cell infiltration, higher tumor proliferation, and poor survival." (PMID 34341887, 2021). "Nevertheless, our present study clearly shows that BCT could be an option for BRCA1/2 variant carriers when the breast tumor is clinically appropriate for the procedure." (PMID 33890992, 2021). "Interestingly, breast tumor samples with somatic damaging (nonsense, frameshift or missense) mutations in BRCA1 or BRCA2 genes showed a higher expression of Signature-3 score than tumors with BRCA1/2 wt genes." (PMID 34139015, 2021). "Interestingly, EZH2 was significantly overexpressed in BRCA1-associated and basal-like breast tumours." (PMID 34287743, 2021). "High-risk screening might facilitate downstaging of detected breast tumor among BRCA1/2 carrier population." (PMID 34540661, 2021). "We found that cyclin E1 is stabilized in BRCA1 mutated breast tumors in association with reduced phosphorylation on cyclin E1 Threonine 62, and high cyclin E1 is associated with decreased overall survival for patients with BRCA1 mutation." (PMID 34465787, 2021). "Moreover, analyses of TCGA tumour data demonstrated that GSK3α and GSK3β mRNA levels are specifically increased in BRCA1/2-mutated breast tumours, suggesting GSK3 as a potential clinical target for tumours lacking BRCA function." (PMID 34389725, 2021). "EN1 and IGF2BP3 were variably expressed in both BRCA1-associated and basal-like breast tumours." (PMID 34287743, 2021). "Interestingly, breast tumours from BRCA1-mutation carriers originate from the luminal cells in the vast majority of cases." (PMID 33755171, 2021). "Drug-efflux transporter genes (ABCB1a, ABCB1b, and ABCB2) encoding multidrug resistance protein 1 (MDR1) were found to be highly expressed and exhibited epithelial-to-mesenchymal transition phenotypes in a PARPi resistant cohort in a murine model of BRCA1-mutated breast tumors." (PMID 33324554, 2020). "Our current studies demonstrating that βarr1 controls the levels of 53BP1 suggest that this circuit may play roles in tumor initiation and therapy resistance of BRCA1 deficient breast tumors." (PMID 31506606, 2020). "Moreover, we tried to utilize PARP inhibition approach in one of the patients in our cohort, as PARP inhibition is synthetically lethal in BRCA-deficient tumors (FDA approved for ovarian, pancreatic, and breast tumors with BRCA1/2 mutation)." (PMID 32377194, 2020). "Interestingly, genomic analysis of 115 BRCA1/2 breast tumors revealed an inverse association between homologous recombination deficiency (HRD) and immunogenicity despite a higher mutational burden and neoantigen load." (PMID 33718107, 2020).
breast tumors (continued). "In addition, we analyzed formalin fixed paraffin embedded (FFPE) breast tumor specimens from BRCA1/2 mutation carriers and found relatively high methylation levels (nearly 80%) at the deltaNp73 promoter (P2) in all tumors, regardless of their subtype." (PMID 32825620, 2020). "Here, the translational control of TRIM45 by BRCA1 that leads to low TRIM45 levels in BRCA1-deficient breast tumors, may represent a novel mechanism contributing to the onco-suppressive role of BRCA1." (PMID 32290274, 2020). "Furthermore, there was consistent association of BRCA1-associated breast tumours with basal-like subtype." (PMID 33081408, 2020). "About 70% of breast tumors arising in BRCA1 mutation carriers are “triple negative”." (PMID 32481735, 2020). "Although in a minor proportion, our data are in accordance with the results published by the CIMBA group, where the authors reported that 77.0% of women with mutations in BRCA1 had grade III breast tumors, compared to only 50.0% of women with mutations in BRCA2." (PMID 31244284, 2019). "A better understanding of the early molecular abnormalities in BRCA1 mutation-carrying breast epithelium could potentially inform development of novel tools to more precisely prevent breast tumors in women with germ-line BRCA1 mutations." (PMID 30995943, 2019). "Ovarian and breast tumors with BRCA1 and BRCA2 mutations are sensitive to the PARP1 inhibitors." (PMID 31856867, 2019). "Here we present a systematic genomic analysis of breast tumors with BRCA1 and BRCA2 mutations." (PMID 31182087, 2019). "However, at least 20%of all breast tumors arising in the BRCA1 germline mutationcarriers express ER (Mavaddat etal., 2012)." (PMID 31067289, 2019). "However, BRCA1-associated basal-like breast tumors originate from luminal progenitor cells, namely, the cell of origin for BRCA1-associated tumors." (PMID 30995943, 2019). "Moreover, a study by Bane and colleagues reported that BRCA2-associated breast tumors are characterized by an increased expression of fibroblast growth factor 1 and fibroblast growth factor receptor 2 compared to BRCA1-associated breast tumors." (PMID 31244284, 2019). "Indeed BRCA1-deficient breast tumors are highly enriched for mutations at R-loop sites located at transcriptional termination regions in the genome." (PMID 30813363, 2019). "Importantly, TNBC accounts for 70% of breast tumors arising in BRCA1 mutation carriers and 16–23% of breast tumors in BRCA2 carriers." (PMID 30909550, 2019). "We therefore analyzed whether the BRCA1/2-mutated tumors have a different pattern of mutational signatures from the sporadic breast tumors." (PMID 31182087, 2019). "In addition, these BRCA1-associated breast tumors tend to be triple-negative for estrogen receptor α (ER-), progesterone receptor (PR-), and HER2 (HER2-), making it more challenging to develop targeted therapies." (PMID 30558184, 2018). "Therefore, the present study attempted to compare the BRCA1 expression in triple-negative with luminal breast tumors and its association with the clinicopathologic characteristics of patients." (PMID 28646826, 2018). "For example, breast tumours from patients with germline mutations in BRCA1 or BRCA2 harbour a greater number of clonal mutations compared with BRCA1/2 wild-type tumours, and in a study of gastric cancer, an association between ATM loss and microsatellite instability has been demonstrated." (PMID 29123260, 2018). "In addition, consistent with a BRCA1-deficiency phenotype, miR-182-overexpressing breast tumor cells are hypersensitive to the inhibitors of poly (ADP-ribose) polymerase I (PARP1)." (PMID 30135399, 2018). "We found that BRCA1 mutation-associated R-loop accumulation only occurs in luminal epithelial cells, which is reminiscent of the lineage-specific cell-of-origin for BRCA1-associated breast tumors." (PMID 30558184, 2018). "Breast tumours arising in BRCA1 mutation carriers most closely resemble basal-like breast tumours." (PMID 30323900, 2018).
breast tumors (continued). "Interestingly, it has been demonstrated that loss of 53BP1 rescues DNA repair defects in BRCA1 deficient cells, thus the dual loss of BRCA1 and 53BP1 in breast tumors is likely to contribute to cancer susceptibility via chromosome instability." (PMID 28415769, 2017). "Thus, the familial breast tumor samples carrying BRCA1/2 germline mutations represent a ‘homogenous’ set of cancers that are driven by HR pathway inactivation." (PMID 29146938, 2017). "Moreover, other reports revealed the function of miRNAs in detecting BRCA genetic or epigenetic alterations in hereditary and sporadic breast tumors or finally, in discerning sporadic and BRCA1 associated basal-like BC." (PMID 28881597, 2017). "Moreover, the normalized expression of CDH1 is significantly reduced in tumours that arise in carriers of BRCA1 mutations relative to sporadic breast tumors." (PMID 28427147, 2017). "Mechanistically, loss of transcriptional inhibition by BRCA1 on β-hCG could be an important event in the tumorigenesis of BRCA1 mutated breast tumors." (PMID 28869585, 2017). "Most BRCA1-associated breast tumours are basal-like yet originate from luminal progenitors." (PMID 28649985, 2017). "We compared our findings to 319 radiation-naive breast cancers and sarcomas processed by the same sequencing and bioinformatics pipeline: 251 breast tumours; 33 breast tumours with pathogenic BRCA1 or BRCA2 germline mutations; 35 osteosarcomas (see Methods for cohort details)." (PMID 27615322, 2016). "Joshi and colleagues have showed progesterone-mediated expansion of the luminal progenitor cells in human breast tissue which is of direct relevance for BRCA1 mutation carriers who have an increased propensity to develop breast tumours with stem cell-like properties." (PMID 27893411, 2016). "Therefore, we performed proteomics of EVs isolated from the same BRCA1-deficient and BRCA1-proficient breast tumor cell lines resulting in 2,149 proteins." (PMID 27566577, 2016). "However, we noted that discrimination was imperfect; a large number of sporadic breast tumors were associated with equal or higher RIPS than breast tumors from mutant BRCA1/2 carriers." (PMID 27788678, 2016). "Further on, we conclude that somatic inactivation of BRCA1 through spliciogenic mutations is, at best, a rare mechanism in breast carcinogenesis, albeit our data detects an excess of likely inactivating AS events in breast tumor samples." (PMID 25884417, 2015). "Sporadic breast tumors tend to display characteristics of BRCA-1 mutation cancers (i.e. BRCAness)." (PMID 26715507, 2015). "It was reported that BRCA1 deficient breast tumors have higher IGF-1R expression." (PMID 26510816, 2015). "However, in spite of the high penetrance, BRCA-1 mutations explain only a small percentage (5-10 %) of breast tumor cases." (PMID 26715507, 2015). "In case of chemotherapy, synthetic lethality could emerge, increasing tumour control by the treatment and thereby improving patient survival, a similar synthetic lethal effect as observed for BRCA1-deficient breast tumours treated with PARP inhibitors." (PMID 26674097, 2015). "Increased expression and activation of the AhR may contribute to epigenetic remodeling during early breast carcinogenesis, whereas loss of BRCA-1 associates with ERα-negativity in hereditary and sporadic breast tumors." (PMID 26715507, 2015). "PALB2 mutation may be associated with triple-negative breast cancer, the same as immunohistochemical features of BRCA1/2 mutation-associated breast tumors." (PMID 26489409, 2015). "We selected 150 FFPE breast tumor DNA samples [47 BRCA1 pathogenic mutation carriers, 65 BRCAx (BRCA1-wild type), 38 BRCA1 test variants] and analyzed a subset (n=54) using the Illumina 450K methylation platform, using the remaining samples for bisulphite pyrosequencing validation." (PMID 26727311, 2015).
breast tumors (continued). "We previously showed a difference in methylation between familial breast tumors with different BRCA1 germline mutations compared to BRCAx, and found that the methylation clusters formed were independent of the intrinsic subtype, and therefore had the potential to be independent of ER status." (PMID 26727311, 2015). "Importantly, we observed that the 13q34 amplification presents increased frequency in BRCA1-defective tumors and seems to be associated with primary breast tumors of basal-like phenotype." (PMID 24870930, 2014). "Among the BRCA1-mutated breast tumors, the triple negative phenotype represents 70-80%." (PMID 25406994, 2014). "Since PTEN loss is an important early initiating event in BRCA1-associated basal-like breast tumours, we hypothesised that it could also be a driver event in HGSOC." (PMID 25608477, 2014). "Breast tumor cells with BRCA1 mutation carriers may have particular sensitivity to platinum agents and relatively less sensitivity to taxanes." (PMID 29147345, 2013). "Gorski and collaborators also demonstrated that BRCA1 and c-Myc form a repressor complex on CDH3 promoter and on other promoters of specific basal genes, representing a potential mechanism to explain the overexpression of key basal markers in BRCA1-deficient breast tumours." (PMID 23405208, 2013). "Taken together, these data indicate that BRCA-negative cells are addicted to AKT/mTOR pathway for their survival and inhibition of mTOR by MET could significantly suppress growth of BRCA1-deficient breast tumors." (PMID 26097796, 2012). "Our findings provide new insights into the mechanism through which BRCA1 may promote commitment of initially bipotent mammary cells towards the luminal lineage, and how loss of this function may predispose cells to become breast tumors of a basal-like type." (PMID 22110403, 2011). "It was previously reported that some BRCA1-deficient breast tumors have enhanced HRR." (PMID 21666281, 2011). "Thus, there is strong evidence to suggest that loss of BRCA1 generates a cancer stem cell capable of initiating and driving breast tumour formation." (PMID 21609478, 2011). "Clinical trials are currently underway to determine the efficacy of PARP inhibitors in treating BRCA deficient breast tumors, which may open new avenues for less toxic therapies that target particular DNA repair pathways in BRCA1 and BRCA2 mutation carriers." (PMID 21037853, 2010). "Furthermore, deletions of chromosome regions harboring GPM6 (4q34.2), CASP3 (4q35.1), and P4HA2 (5q23.3) have been shown to be associated with breast tumors from BRCA1 mutation carriers." (PMID 20174566, 2010). "Primary breast tumors from BRCA1 mutation carriers have unique pathology, including high histological grade, atypical medullary histotype, high rates of cellular proliferation, pushing margins and infiltrating lymphocytes, and are frequently ER, PR, and HER2 negative (triple negative)." (PMID 21037853, 2010). "Additionally, breast tumors occurring in individuals with germline BRCA1 or BRCA2 mutations typically fall into distinct subtypes." (PMID 20576095, 2010). "Importantly, clustering on the basis of these regions separated BLBCs and BRCA1-mutated breast tumors from luminal breast tumors." (PMID 21118481, 2010).